APEH (acylaminoacyl-peptide hydrolase)
Description:
Aminopeptidase involved in the degradation of N(alpha)- acylated peptides. Displays exopeptidase activity toward N-formyl and N-acetyl peptides with a preference for dipeptide substrates (By similarity). Catalyzes the hydrolysis of the N-terminal peptide bond of an N-acetylated peptide to generate an N-acetylated amino acid and a peptide with a free N-terminus. It preferentially cleaves off Ac-Ala, Ac-Met and Ac-Ser (By similarity). Hydrolyzes N-formylated peptides likely arising from N-terminal proteolytic cleavage of bacterial and mitochondrial proteins. May act sequentially with ACY1 in the degradation of N-acylated peptides: APEH first cleaves N-acylaminoacids from N-acylated peptides, then ACY1 further hydrolyzes the N-acylaminoacid into free aminoacid and a carboxylate (By similarity). Displays endopeptidase activity involved in the degradation of oxidized and glycated proteins.
Synonyms: AARE; APH; OPH; D3F15S2; D3S48E; DNF15S2; ACPH
Tractability: Antibody: its Gene Ontology location is reachable by antibodies, with high confidence. PROTAC: ubiquitination databases record sites on it; its protein half-life has been measured.
Target class: Enzyme; Serine protease; Serine protease SC clan; Protease; Serine protease S9C subfamily
Gene: Protein-coding gene on chromosome 3 (49,673,981 to 49,683,971, forward strand). Ensembl gene ENSG00000164062.
Subcellular location: Cytoplasm
Subcellular location (Human Protein Atlas): Cytosol
Pathways (Reactome):
Immune System: Neutrophil degranulation
Metabolism of proteins: Eukaryotic Translation Termination
Gene Ontology:
Molecular function: identical protein binding; omega peptidase activity; protein binding; RNA binding; serine-type endopeptidase activity; peptidase activity; serine-type peptidase activity
Biological process: amyloid-beta metabolic process; proteolysis; translational termination
Cellular component: cytoplasm; cytosol; extracellular exosome; extracellular region; ficolin-1-rich granule lumen
Genetic constraint (gnomAD): Loss-of-function variants: 75 observed, 104.42 expected, observed/expected ratio (o/e) 0.72, 90% interval 0.6 to 0.87. The upper end of that interval is the gene's LOEUF score, 0.87, which puts it in group 3 of 6, group 1 being the genes least tolerant of losing a copy. Missense variants: 863 observed, 962.95 expected, observed/expected ratio (o/e) 0.9, 90% interval 0.85 to 0.95. Synonymous variants: 344 observed, 367.61 expected, observed/expected ratio (o/e) 0.94, 90% interval 0.86 to 1.02.
Homologues: Orthologues: chimpanzee APEH (98% identical), macaque APEH (95% identical), dog APEH (94% identical), guinea pig APEH (94% identical), rabbit APEH (93% identical), pig APEH (92% identical), rat Apeh (92% identical), mouse Apeh (91% identical), tropical clawed frog apeh (64% identical), zebrafish apeh (61% identical), Caenorhabditis elegans dpf-5 (35% identical). Paralogues in human: DPP6 (17% identical), DPP10 (16% identical), FAP (15% identical), DPP4 (15% identical), DPP9 (14% identical), DPP8 (14% identical).
Diseases named in the same sentence as APEH in open-access papers:
APEH is named in the same sentence as 29 diseases in open-access papers, as found by Europe PMC text mining. Sharing a sentence is not in itself a finding about the gene and the disease. The quoted sentences say what the papers report.
anemia (1 paper, 2018). A reduction in the number of red blood cells, the amount of hemoglobin, and/or the volume of packed red blood cells. "On the basis of Cox regression analysis (after adjustment for gender, age, histopathological diagnosis, stage of disease - TNM classification anemia before the treatment and tobacco smoking status) we found that CC genotype of APEH gene was an independent prognostic factor." (PMID 30038710, 2018).
Chagas disease (1 paper, 2021). A parasitic infection caused by Trypanosoma cruzi. "All proteins in this family have been implicated in various clinical conditions; prolyl endopeptidase (PREP; OMIM 600400), oligopeptidase B (OpdB) (role in host cell invasion by Trypanosoma cruzi, Chagas disease), acylaminoacyl‐peptidase (APEH; OMIM 102645), and dipeptidase IV (DPPIV; OMIM 102720)." (PMID 34612606, 2021).
Cognitive impairment (1 paper, 2018). Abnormal cognition is characterized by deficits in thinking, reasoning, or remembering. "Because of the neuronal implications of APEH, we believed that this enzyme would be a useful marker for chronic exposure associated with cognitive impairment, and/or a biomarker of acute exposure to anticholinesterase pesticides." (PMID 29718943, 2018). "The proposed biomarker for cognitive impairment was acylpeptide hydrolase (APEH) found in erythrocytes, and AChE and BChE activity levels were used as reference enzymes." (PMID 29718943, 2018). "Along with attempting to find a correlation between a clinical outcome like cognitive impairment and APEH activity, we also attempted to establish the pattern of enzyme inhibition during spraying." (PMID 29718943, 2018). "The relationship between chronic exposure to pesticides, cognitive impairment or neurodegenerative diseases, and the role of APEH activity as an early biomarker of this pathological progression, remains to be elucidated." (PMID 29718943, 2018). "It is important to keep in mind that the ultimate reason to measure APEH activity in our study was to determine if it serves as a biomarker of cognitive impairment in individuals chronically exposed to pesticides." (PMID 29718943, 2018).
dementia (1 paper, 2009). Loss of intellectual abilities interfering with an individual's social and occupational functions. "If its role is proven in animal models, APEH can serve as an important therapeutic target for slowing the Aβ induced neurodegeneration and dementia in AD." (PMID 19627603, 2009).
fibrosis (1 paper, 2024). the formation of excess fibrous connective tissue in an organ or tissue in a reparative or reactive process. "In line with this, we found an increased ACE, MMP2, and MMP7 mRNA expression, but also reduced APEH, ECE1, MBP, and NEP in samples with an advanced fibrosis grade." (PMID 39201455, 2024).
head and neck cancer (1 paper, 2018). A primary or metastatic malignant neoplasm affecting the head and neck. "The study purpose was to examine the correlation between SNP in the regulatory region (c.-521G>C, rs4855883) of APEH gene as well as the incidence and severity of radiotherapy (RTH) induced oral mucositis (OM) and overall survival (OS) in head and neck cancer (HNC) patients." (PMID 30038710, 2018).
neuroblastoma (1 paper, 2009). Neuroblastoma (NB) is the most common solid, extracranial childhood tumor. "We recently purified to homogeneity, as judged by a single band on a silver stained gel, and identified by mass spectrometry, the serine protease acyl peptide hydrolase (APEH) as an enzyme that degrades Aβ in SKNMC neuroblastoma cells." (PMID 19627603, 2009).
non-small cell lung carcinoma (1 paper, 2012). A group of at least three distinct histological types of lung cancer, including non-small cell squamous cell carcinoma, adenocarcinoma, and large cell carcinoma. "A recent paper investigating PORCN in Non Small Cell Lung Carcinoma illustrated that loss of PORCN downregulates S100P at the mRNA and protein levels in a β-catenin independent manner, similar to what we have shown for APEH." (PMID 22509316, 2012).
Obesity (1 paper, 2021). Accumulation of substantial excess body fat. "Concordantly, MR analysis revealed higher expression of APEH to be negatively associated with the risk for obesity, immature reticulocyte count and positively with CNS/lifestyle traits associated with higher cognition." (PMID 33574266, 2021).
renal cell carcinoma (1 paper, 2016). "APEH (acylaminoacyl-peptide hydrolase) plays an important role in destroying oxidatively damaged proteins in living cells and deletion of APEH locus have been found in small cell lung carcinoma and renal cell carcinoma." (PMID 27690302, 2016).
turban tumor syndrome (1 paper, 2011). "The cylindromatosis/turban tumor syndrome gene (CYLD) on chromosome 16 ranked highest, followed by acylaminoacyl-peptidase (APEH), dystroglycan (DAG1), macrophage-stimulating protein (MST1) and ubiquitin-specific peptidase 4 (USP4), all located on chromosome 3." (PMID 21931648, 2011).
cancer (7 papers, 2011 to 2023). A tumor composed of atypical neoplastic, often pleomorphic cells that invade other tissues. "Genes PRKCZ (Protein Kinase C Zeta), FGR (Src family protein), KDM4B, MPO, COL11A1, FUT4 (Fucosyltransferase IV), and APEH (acylpeptide hydrolase) are directly associated with tumor aggressiveness, growth, and migration, and invasiveness, resulting in poor clinical outcome in cancer patients." (PMID 38086861, 2023). "The genes assayed were neuroendocrine-associated genes (INSM1, ASCL1, NRCAM, and SNAP25), one gene centered in the gene regulatory network (NUF2), and five possibly cancer-associated genes (PTP4A3, RFC4, REST, APEH, and FBLN2)." (PMID 34395507, 2021). "Our study supports a previously unrecognized role of APEH as a negative effector of proteasome activity by an unknown mechanism and opens new perspectives for the development of strategies aimed at modulation of cancer progression." (PMID 22016782, 2011).
APEH also shares sentences with these, for which no sentence is quoted: Alzheimer disease (2 papers); prostate carcinoma (2); Acute hepatitis (1); bacterial vaginosis (1); Bovine mastitis (1); cholestasis (1); Encephalopathy (1); endometriosis (1); Hyperammonemia (1); infection (1); neonatal encephalopathy (1); neurodegenerative disease (1); Parkinsonism (1); prostate tumors (1); Seckel syndrome (1); small cell lung carcinoma (1); tumor (1).